TK1 (thymidine kinase 1)
Diseases named in the same sentence as TK1 in open-access papers (continued):
Sharing a sentence is not in itself a finding about the gene and the disease.
lymphoma (continued). "Mean serum TK1 activity and TK1 protein in dogs with lymphoma that were in complete remission (CR) were not significantly different from the TK1 in healthy controls (P = 0.342; P = 0.417)." (PMID 26366881, 2015). "The AroCell TK 210 ELISA could not detect any TK1 protein in extracts from the lymphoma or the healthy dogs." (PMID 37808109, 2023). "However, despite its clinical utility in other species, as well as the recent study suggesting its use in horses, our clinical impression has been that TK1 is not a clinically useful marker for lymphoma in horses." (PMID 34359096, 2021). "It is therefore reasonable that horses without a histopathologic diagnosis of lymphoma that displayed elevated TK1 in our sample could represent a pre‐cancerous group." (PMID 34359096, 2021). "For instance, TK1 levels do not correlate with the prognosis of DLBCL following CHOP-based chemotherapy and the survival of multicentric lymphoma." (PMID 39682357, 2024). "With these anti-TK1 antibodies, TK1 protein concentration in serum (STK1) is now useful for prognosis, treatment monitoring, and discovery of recurrence of various types of solid tumours, in addition to lymphoma and leukaemia, showing an increasingly important role of TK1 in the clinical setting." (PMID 22247653, 2011).
colorectal cancer (16 papers, 2014 to 2025). A primary or metastatic malignant neoplasm that affects the colon or rectum. "In contrast to malignancies such as lung, breast, or colorectal cancer—where TK1-mediated pathways such as Rho GTPase or MAPK signaling have been implicated in tumor progression—relatively little is known about the mechanistic involvement of TK1 in OSCC." (PMID 40564887, 2025). "TK1 plays a moderate role as a diagnostic tumor marker for cancer patients, and it is a potential clinical biomarker for the treatment of lung, breast, and colorectal cancer." (PMID 33711952, 2021). "Moreover, acquired resistance to trifluridine in the colorectal cancer cell line DLD1 is associated with loss of function of TK1 due to a point mutation in its gene, and resistance ensues in these cells through knockout of the gene through CRISPR/Cas9." (PMID 34884270, 2021). "TK1 mediates the synergistic antitumor effects of ubenimex and celecoxib through regulation of the colorectal cancer cell cycle." (PMID 39803822, 2025). "This study generated TK1-specific-knock-out human colorectal cancer cell lines and demonstrated that TK1 is essential for cellular sensitivity to FTD." (PMID 31138881, 2019). "We also report clinical data from The Cancer Genome Atlas (TCGA), where we explore TK1 gene expression levels, showing that TK1 levels are upregulated in lung, breast, and colorectal cancer patients compared to their healthy normal patients." (PMID 30214377, 2018). "We conclude that TK1 is a potential clinical biomarker for the treatment of lung, breast, and colorectal cancer." (PMID 30214377, 2018). "We also analyzed RNA-Seq data from The Cancer Genome Atlas (TCGA) to assess differential expression of the TK1 gene in lung, breast, and colorectal cancer patients." (PMID 30214377, 2018). "Since TK1’s levels are proliferation-dependent, we wanted to test whether healthy normal colon cells expressed TK1 on their membrane to ascertain the clinical relevance of TK1 as biomarker target in colorectal cancer patients." (PMID 30214377, 2018). "Additionally, dual staining for TK1/CD31 was able to more accurately identify tumor vessels in colorectal carcinoma than staining for other markers, suggesting that TK1/CD31 dual staining may be a useful predictor of tumor responses to anti-angiogenic therapy." (PMID 31589613, 2019). "Moreover, serum TK1 has been found to be elevated in several hematological and solid tumors including breast, lung, colorectal cancer, among others, and high serum TK1 levels usually correlate with cancer grade and stage, increased T-values, and increased tumor size." (PMID 30214377, 2018). "In a previous work, we have demonstrated that SFRE inhibited thymidine kinase 1 (TK1) and thymidylate synthase (TYMS) synergising with 5- fluorouracil (5-FU) in the inhibition of colorectal cancer cell lines proliferation." (PMID 36439419, 2022). "The activity of TK1 was examined in a study of colorectal cancer cell line HCT-116, which was knocked down for TK1 through CRISPR/Cas9." (PMID 34884270, 2021). "Thymidine kinase 1 (TK1), CA19-9, and CA72-4 combined with other carcinoembryonic antigen exhibited better detection ability of GC and colorectal cancer (CRC)." (PMID 34659407, 2021). "In the context of EGFR inhibition in a wild-type KRAS colorectal cancer cell line we show that a lack of TK1 attenuation, and thus similar [18F]-FLT PET, in treated xenografts reflected PI3K-mTOR activity." (PMID 25247710, 2014). "Furthermore, tissue staining for TK1 has been used to identify activated tumor vessels involved in angiogenesis in colorectal cancer (CRC) patients; indeed, in studies involving double immunostaining for both CD31 and TK1, results showed TK1 to be a highly specific marker for activated vessels." (PMID 33292474, 2020).
colorectal cancer (continued). "This study shows that TK1 localizes on the cell membrane of NCI-H460, A549, MCF7, MDA-MB-231, SW620, and HT-29 cells lines and on the membrane of colorectal cancer cells and not on the membrane of healthy colorectal cells from patients." (PMID 30214377, 2018).
hepatocellular carcinoma (12 papers, 2020 to 2026). A malignant tumor that arises from hepatocytes. "Next, a literature search was conducted to focus on proteins specifically associated with liver disease in general, which selected 20 proteins, seven of which (i.e., CEP55, CLIC1, EPS15L1, G6PD, KIF11, SLC1A5, and TK1) were found to be specifically associated with hepatocellular carcinoma." (PMID 37627157, 2023). "In hepatocellular carcinoma, TK1 drives tumor progression in an enzyme-dependent and -independent manner." (PMID 39803822, 2025). "Previous results showed that the levels of serum TK1 (thymidine kinase 1) in the primary hepatic carcinoma group were significantly higher than those in the control group and the benign group (P ≤ 0.05) (Shen-Jie & Li, 2018; Zhang, Lin & Li, 2015)." (PMID 33552715, 2021). "In this study we investigated if thymidine kinase 1 in blood could be used to discover patients with hepatocellular carcinoma and show the results of their treatment." (PMID 34258026, 2021). "However, the relationship of TK1 expression with immune cell infiltration and its prognostic value in hepatocellular carcinoma (HCC) are still unknown." (PMID 35127491, 2021). "The association of UBE2C with RBP7, alongside other upregulated genes such as TK1 and TYMS, underscores its potential role in hepatocellular carcinoma progression and highlights UBE2C as a critical target for therapeutic intervention in this context." (PMID 41301068, 2025). "Among them, CDK1, CHEK1, TYMS, KIF11, MMP12, TK1 and CA12 were differentially highly expressed in hepatocellular carcinoma tissues." (PMID 38842135, 2024). "Moreover, TK1 appears to contribute to metabolic reprogramming through interaction with PRMT1, as reported in hepatocellular carcinoma, where it promotes glycolysis and tumor aggressiveness." (PMID 41584726, 2026). "Also, the expression of YBX1 mRNA significantly positively correlated with RRM2, TK1, and TYMS mRNA expression in 374 human hepatocellular carcinoma samples (TCGA)." (PMID 32587247, 2020). "A meta-analysis was conducted to evaluate the clinical significance of serum thymidine kinase 1 protein concentration (STK1p) in distinguishing between hepatocellular carcinomas (HCC) and non-HCC for predicting early progression and monitoring the response to transarterial chemoembolization in HCC." (PMID 34258026, 2021).
lung adenocarcinoma (12 papers, 2018 to 2025). A carcinoma that arises from the lung and is characterized by the presence of malignant glandular epithelial cells. "For instance, in lung adenocarcinoma, TK1 overexpression has been shown to promote tumor growth and metastasis through Rho GTPase activation and downstream regulation of GDF15." (PMID 40564887, 2025). "In lung adenocarcinoma, TK1 has been shown to promote tumor progression through activation of Rho GTPase signaling and transcriptional regulation via the MAPK–MAZ axis." (PMID 40564887, 2025). "Patients with high expression of TK1 showed higher stromal invasion grade and poor survival in lung adenocarcinoma." (PMID 35620468, 2022). "Recent studies on the suppression of TK1 in cancer cells have shown that the silencing of TK1 decreases the capacity of lung adenocarcinoma, pancreatic and thyroid carcinoma cells to proliferate, migrate or make mesenchymal transitions." (PMID 35239730, 2022). "Further, high expression levels of UBE2T, TK1, and KPNA2 were associated with poor survival rates of patients with lung adenocarcinoma in TCGA data." (PMID 35884546, 2022). "Careful analysis of prostate tumors, ovarian serous adenocarcinoma, and lung adenocarcinoma have demonstrated that TK1 is also more sensitive and reliable as a biomarker than Ki-67 and PSA." (PMID 33292474, 2020). "In this study, we performed TK1 knockdown and found that this protein is necessary for lung adenocarcinoma (LUAD) tumor growth and metastasis." (PMID 31589613, 2019). "Our analysis reveals that TK1 levels are upregulated in both lung adenocarcinoma and lung squamous cell carcinoma, breast invasive carcinoma, and colorectal adenocarcinoma patients." (PMID 30214377, 2018). "In addition, the missing TK1 has been shown to inhibit the growth and metastatic ability of lung adenocarcinoma in vitro and in mice by reducing the expression of growth differentiation factors." (PMID 35190747, 2022). "Here, we show that thymidine kinase 1 (TK1) is significantly overexpressed in tumor samples from lung adenocarcinoma (LUAD) patients relative to normal controls, and this TK1 overexpression is associated with significantly reduced overall survival and cancer recurrence." (PMID 31589613, 2019). "Lung adenocarcinoma and lung squamous carcinoma seem to be the malignancies with the most differential expression of TK1 between normal and malignant patients, followed by breast invasive carcinoma, where we could also observe clear differential expression." (PMID 30214377, 2018).
leukemia (10 papers, 2011 to 2025). A malignant (clonal) hematologic disorder, involving hematopoietic stem cells and characterized by the presence of primitive or atypical myeloid or lymphoid cells in the bone marrow and the blood. "Nevertheless, most patients with BCP-ALL group and high TK1 levels had high-risk factors (age and leukocytes), hence the substantial increase in TK1 levels in patients with AL, along with its correlation to leukemia subtype and high-risk stratification." (PMID 37627214, 2023). "The results showed that TK1 exits as high MW oligomers which are active in both healthy and leukemia sera." (PMID 25881026, 2015). "A reason for this could be that there was a larger proportion of inactive TK1 in serum from patients with solid tumors compared to those seen in sera from leukemia patients." (PMID 27079872, 2016).
bladder cancer (9 papers, 2012 to 2025). "Specifically, m5C-mediated ALYREF recognizes RABL6 and TK1 mRNA m5C modification through its K171 domain, enhancing mRNA splicing and stability to increase bladder cancer malignancy." (PMID 40809690, 2025). "Through its K171 domain, ALYREF recognizes RABL6 and TK1 mRNA m5C modification, promoting their mRNA splicing and stability to increase bladder cancer malignancy." (PMID 40809690, 2025). "Taken together, our findings support that the CASC9/miR-195-5p/TK1 axis is a critical pathway in the tumorigenesis and progression of bladder cancer, implicating a new therapeutic direction for the treatment of bladder cancer." (PMID 35578597, 2022). "Mechanistically, through FISH experiments, luciferase reporter experiments, and RIP experiments, we proved that CASC9 regulated the expression of TK1 by adsorbing miR-195-5p, thereby exerting an oncogenic effect in bladder cancer." (PMID 35578597, 2022).
gastric cancer (9 papers, 2018 to 2026). A primary or metastatic malignant neoplasm involving the stomach. "So far, TK1 has been applied as a biomarker in the lung, breast, prostate, and gastric cancer, and its overexpression was associated with poor prognosis." (PMID 37373974, 2023). "Another study offered a combination of TK1+ CEA+ CA19-9 + CA72-4 for diagnostic sensitivity of 80.8-87% for CRC and 88.2% for gastric carcinoma." (PMID 33247667, 2020).
liver cancer (8 papers, 2015 to 2025). An epithelial or non-epithelial malignant neoplasm that arises from the liver. "Single-cell sequence analysis of liver cancer tissue revealed that T cells gamma delta had the highest expression of TK1." (PMID 35127491, 2021). "We found that the thymidine conjugate had varied activities in liver cancer cells with different levels of TK1 and TYMP." (PMID 25881156, 2015). "Therefore, the results from our siRNA suppression and viral overexpression studies indicated that high levels of cytosolic TK1 were responsible for the cytotoxicity of dT-QX in liver cancer cells while high levels of TYMP counteracted the biological activity." (PMID 25881156, 2015). "Knockdown of lincNMR, YBX1, TK1, and TYMS also significantly inhibited the colony-formation capacity of liver cancer cells." (PMID 32587247, 2020). "In summary, their regulation, their association with survival, and their correlation of expression links lincNMR, YBX1, RRM2, TK1, and TYMS to liver cancer and to each other, respectively." (PMID 32587247, 2020). "Next, we found RRM2, TK1, and TYMS to be strongly and significantly induced by about ten-, six- and fourfold, respectively, in liver cancer patient datasets from TCGA." (PMID 32587247, 2020). "LincNMR and YBX1 mRNA expression significantly correlate in liver cancer patient samples as well as with RRM2, TK1, and TYMS mRNA expression." (PMID 32587247, 2020). "In this study, we reported the involvement of TK1 and TYMP in the biological activity of thymidine analog dT-QX in different liver cancer cell lines, methods to enhance the anticancer selectivity and in vivo study with a mouse tumor model." (PMID 25881156, 2015). "Indeed, RRM2 and TK1 were decreased by YBX1 inactivation, which is involved in nucleotide metabolism in liver cancer cells." (PMID 40812419, 2025). "The lincNMR expression level significantly positively correlated with RRM2, TK1, and TYMS mRNA levels in HCC patient samples, further corroborating the strong link between lincNMR, these three regulators of nucleotide metabolism, and liver cancer." (PMID 32587247, 2020). "By taking advantage of low levels of TK1 and TYMP in normal liver tissue, the use of anticancer thymidine conjugate combined with TYMP suppression could directly target thymidine salvage pathway in liver cancer cells with various levels of TYMP addressed as tumor heterogeneity to be fully inhibited." (PMID 25881156, 2015).
melanoma (8 papers, 2014 to 2023). A malignant, usually aggressive tumor composed of atypical, neoplastic melanocytes. "TK1 is an enzyme involved in nucleotide biosynthesis and is elevated in many cancers, including melanoma." (PMID 37377898, 2023). "In vitro and in vivo experiments confirmed that TK1 displayed a protumorigenic role by activating the proliferation and migration of melanoma cells." (PMID 35311151, 2022). "Our data show that in mutNRAS melanoma cells elevated TK1 activity contributes to enhanced pyrimidine salvaging." (PMID 24941944, 2014). "In summary, mutNRAS melanoma cells are more efficient in nucleotide salvaging than mutBRAF melanoma cells, which is at least part due to enhanced TK1 expression and IMPDH activity." (PMID 24941944, 2014). "Notably, ADI‐PEG20 has been reported to increase pyrimidine salvage in melanoma cell lines in vivo via upregulation of thymidine kinase 1, highlighting differential biology compared with arginine tumour auxotrophs of epithelial origin." (PMID 35466524, 2022). "Expression of key nucleotide synthesis and proliferation enzymes thymidylate synthase (TS) and thymidine kinase 1 (TK1) was evaluated in differentiated (MITFhigh [microphthalmia‐associated transcription factor] IGR1) and invasive (MITFmediumIGR37) melanoma cells." (PMID 28608446, 2017). "Indeed, we found a significant overexpression of TK1 in mutNRAS cells compared to mutBRAF cells in our panel of melanoma cell lines." (PMID 24941944, 2014). "This, together with the fact that mutNRAS cells express higher levels of TK1 and consequently are more effective in using thymidine for DNA synthesis, provides strong evidence that mutNRAS melanoma cells are significantly more efficient in nucleotide salvaging." (PMID 24941944, 2014). "Further analysis revealed that the growth-inhibitory effects mediated by DTIC were rather due to interference with nucleotide salvaging, and that NRAS mutant melanoma cells exhibit higher activity of the nucleotide synthesis enzymes IMPDH and TK1." (PMID 24941944, 2014). "In line with this, we found increased expression of the key enzymes of nucleotide salvaging HGPRT (HPRT1), thymidine kinase (TK1) and APRT in melanoma (primary and metastatic) compared to normal skin and benign nevi." (PMID 24941944, 2014).